MMP14 (matrix metallopeptidase 14)
Diseases named in the same sentence as MMP14 in open-access papers (continued):
Sharing a sentence is not in itself a finding about the gene and the disease.
ovarian carcinoma (continued). "By searching on ‘MMP-14 AND ovarian cancer’, a total of 94 references were found, of which 33 were excluded after screening of the titles and abstracts." (PMID 34344453, 2021). "From this systematic review of the literature concerning MMP-14 in ovarian cancer it becomes clear that MMP-14 plays various important roles in the pathophysiology of ovarian cancer." (PMID 34344453, 2021). "MMP-14 is crucial for the shedding of ovarian cancer cells from primary tumors into the peritoneal cavity where they accumulate as multicellular aggregates for stromal invasion and further dissemination." (PMID 35047406, 2021). "Aside from that, UCA1 was indicated as a sponge for miR-485-5p in ovarian cancer, thus increasing matrix metallopeptidase 14 (MMP14) expression and enhancing the metastasis." (PMID 29368602, 2018). "In other studies of MMP-14 serum levels specifically among breast and ovarian cancer patients, circulating MMP-14 levels were higher in comparison with healthy individuals." (PMID 30532247, 2018). "In 97 patients with ovarian cancer, MMP-14 and CD44 expression as determined by immunohistochemistry was investigated in relation to EMT-like changes." (PMID 27590006, 2016). "In this study with long-term follow-up, the independent prognostic value of MMP-14 and MMP-2 expression in ovarian cancer is limited to a role in PFS for stromal MMP-14 expression and epithelial MMP-2 expression." (PMID 27038607, 2016). "According to previous studies demonstrating a direct link between ET-1 and MMP14 in directing ovarian cancer cell invasion, it is likely that the up-regulation/activation of MMP14 driven by ET-1 is responsible for the enhanced invasion of HG-SOC cells in the tumouroids." (PMID 39503511, 2024). "Additionally, stromelysin MMP3 was unchanged, while membrane-type MMP (MMP14) was lower in ovarian cancer as compared to control samples." (PMID 38397798, 2024). "Only a limited number of studies report on the role of MMP-14 in angiogenesis in ovarian cancer." (PMID 34344453, 2021). "In addition, active MMP-14 promotes ectodomain shedding of MUC16/CA125 in ovarian cancer cells, restrains adhesion and promotes invasion of cancer cells in the peritoneum." (PMID 35047406, 2021). "In March 2020, a search in Pubmed was performed with MMP-14 and ovarian cancer as search terms." (PMID 34344453, 2021). "This may be due to several limitations in the studies, but also to the fact that in ovarian cancer other prognostic factors may overrule the role of MMP-14." (PMID 34344453, 2021). "In order to evaluate the role of MMP-14 in ovarian cancer, a systematic review was conducted." (PMID 34344453, 2021). "There is scant evidence of the effect of MMP-14 expression on proliferation in ovarian cancer." (PMID 34344453, 2021). "The first study on the role of MMP-14 in ovarian cancer was performed in 1996." (PMID 34344453, 2021). "Furthermore, studies on circulating levels of MMP-14 in breast and ovarian cancers concluded that MMP-14 levels appeared elevated in cancer patients compared to controls." (PMID 30532247, 2018). "In search for prognostic markers that could be useful in managing ovarian cancer, we focused on MMP-14 and MMP-2." (PMID 27038607, 2016). "Thus the independent prognostic value of MMP-2 and MMP-14 expression in ovarian cancer is limited." (PMID 27038607, 2016). "Among these candidate targets, however, matrix metalloproteinase 14 (MMP14) demonstrates gene expression that is both high and negatively correlated with survival in ovarian cancer patient cohorts." (PMID 40985572, 2025). "Most of the tested metalloproteinases upregulated mRNA expression in both FIGO I/II and FIGO III/IV stages of ovarian cancer (MMP1, MMP13, MMP2, MMP9, MMP10, MMP7, MMP12 and MMP14) indicating profound modifications of the extracellular matrix." (PMID 38397798, 2024).
ovarian carcinoma (continued). "Having investigated a regional cohort of 94 ovarian cancer patients by means of semiquantitative immunohistochemistry for MMP-14 and MMP-2, we found that epithelial MMP-14 and epithelial MMP-2 expression correlate." (PMID 27038607, 2016). "From this cohort study on MMP-14 and CD44 expression in ovarian cancer, we conclude that the subgroup of patients with positive expression of both MMP-14 and CD44 had type-I tumors with poor prognosis despite complete debulking." (PMID 27590006, 2016). "In ovarian cancer, overexpression of MMPs such as MMP-2, MMP-7, MMP-9, MMP-11 and MMP-14 has been reported and correlated with invasion and metastasis." (PMID 27038607, 2016). "The aim of the present study is to evaluate the prognostic value of MMP-14 and MMP-2 expression in ovarian cancer, as determined by semi-quantitative immunohistochemistry, in a large regional cohort." (PMID 27038607, 2016). "This study was designed to determine the prognostic value of MMP-14 and MMP-2 expression in ovarian cancer with data on long-term follow-up." (PMID 27038607, 2016). "MMP-14 and MMP-2 also appear to be overexpressed in serous and mucinous malignant ovarian tumor epithelium, while benign and borderline tumors show lower levels of expression." (PMID 27038607, 2016). "Downregulation of HOXD10 expression by miR-10b overexpression may induce an increase in prometastatic gene products, such as MMP14 and RHOC, and contribute to the acquisition of a metastatic phenotype by epithelial ovarian cancer cells." (PMID 36213580, 2022). "Though MMP’s and ovarian cancer were reviewed before, no systematic review or meta-analysis on the role of MMP-14 alone in ovarian cancer has yet been published." (PMID 34344453, 2021). "After exclusion of the references not on MMP-14 or ovarian cancer or not in English, the studies found were classified into two categories: basic research and clinicopathological research." (PMID 34344453, 2021). "Although the development of advanced tumours is mediated through several pathways, MMP-14 expression occurs in most advanced-stage ovarian cancers and not in all early-stage tumours." (PMID 34344453, 2021). "The following exclusion criteria were determined: 18 studies were not on MMP-14, 11 studies were not on ovarian cancer and 4 studies were in Chinese." (PMID 34344453, 2021). "Earlier reports indicated a prognostic value for both MMP-14 and MMP-2 in ovarian cancer." (PMID 27038607, 2016). "In ovarian cancer cells, polyomavirus enhancer activator 3 (PEA3) is able to induce MMP-14 expression via direct binding to its promoter, and knockdown of PEA3 reduces the MMP-14 levels." (PMID 27259238, 2016). "A previous study has also shown that MMP-14 could activate MMP2, both of which appeared to play important roles in regulating cell growth and proliferation by controlling matrix remodeling in aggressive ovarian cancer cells." (PMID 31406154, 2019). "Altogether, these findings indicate that MMP14, a zinc (Zn2+)‐dependent endopeptidase, and NCOR2, a transcriptional corepressor, are additional promising candidate targets of the autoantibodies from our original study and may become accessible to circulating ligands in ovarian cancer." (PMID 40985572, 2025). "Although we have found that, for these reasons, EMT-like changes does not indicate prognosis in ovarian cancer, some of our results are consistent with the hypothesis that EMT is stimulated by CD44 and MMP-14 expression." (PMID 27590006, 2016).
glioblastoma (46 papers, 2006 to 2025). The most malignant astrocytic tumor (WHO grade IV). "Previously, we showed that Mmp14 levels are increased in glioblastoma-associated microglia in vitro." (PMID 32299465, 2020). "The matrix metalloproteinase-14 (MMP14) promoter was selected as the strongest promoter able to limit gene expression to myeloid cells infiltrating brain metastasis or glioblastoma (GBM) in mice." (PMID 40089746, 2025). "One method of probe activation uses a FRET-quenched bifunctional probe targeting MMP-14, an enzyme overexpressed in glioblastoma." (PMID 35406390, 2022). "Though MMPs are not typically viewed as important metabolic modulators, there is emerging evidence that MMP-2, MMP-9, and MMP-14 are potent modulators of cholesterol metabolism, a crucial pathway in glioblastoma growth and invasion." (PMID 34277624, 2021). "MMP2 is secreted by glioblastoma cells in a pro-form (pro-MMP2) which needs to be cleaved by Mmp14 (MT1-MMP) to be active." (PMID 32299465, 2020). "Patients with treated glioblastoma exhibit strong level of MMP14 immunoreactivity compared to the untreated cases." (PMID 24156018, 2013). "Furthermore, miR-133b has also been previously proven to suppress glioblastoma cell migration and invasion by targeting MMP14." (PMID 31842978, 2019). "For example, overexpressing transmembrane and cytoplasmic domain of MMP14 in a human adenocarcinoma cell line was shown to enhance glucose uptake (Sakamoto, Niiya & Seiki, 2011) and glucose-6-phosphate transporter (G6PT) gene expression is upregulated in MMP14 silenced human glioblastoma cells." (PMID 27478693, 2016). "Additionally, extracellular vesicles from glioblastoma cells are also known to influence primary human microglia by increasing their expression of matrix metalloproteinase 14 (MMP14), vascular endothelial growth factor (VEGF), and IL-6, thereby making them more pro-tumorigenic." (PMID 34503065, 2021).
lung carcinoma (45 papers, 2008 to 2026). "In a follow-up study, it was shown that NANOS1 is overexpressed in invasive lung carcinomas, which cause an upregulation of MMP14 (MT1-MMP) on both RNA and protein levels." (PMID 36012673, 2022). "MMP-14 deficient H1264 lung cancer cell lines are unable to activate TGFβ via αvβ8, whilst the restitution of MMP-14 rescues αvβ8-mediated TGFβ activation." (PMID 31438626, 2019). "Current evidence indicates that BSP enhances breast and prostate cancer cell survival through RGD-integrin MEK/ERK signalling and facilitates anoikis resistance in lung cancer via miR-150-5p/MMP-14, ultimately supporting metastatic colonisation." (PMID 41554710, 2026). "In vivo, A-549 cells injected into the caudal artery of nude mice show BSP-dependent miR-150-5p downregulation, MMP-14 upregulation, and enhanced anoikis resistance, thereby promoting lung cancer metastasis (8 weeks)." (PMID 41554710, 2026). "Western bolt and qRT-PCR were used to validate the expression of MMP14 in both lung cancer cell line A549 and normal bronchial epithelial cell line BEAS-2B." (PMID 40407957, 2025). "Results indicated a significant upregulation of MMP14 in lung cancer cells, which in line with the bioinformatics analysis findings." (PMID 40407957, 2025). "Our in vitro results showed that downregulation of MMP14 inhibited the cloning, proliferation and invasion of lung cancer cells, which is consistent with the previous observation that MMP14 promotes the migration and invasion of lung adenocarcinoma cells." (PMID 40407957, 2025). "To summarize, the current study demonstrated that BSP promotes MMP‐14‐dependent resistance to anoikis in human lung cancer cells by inhibiting the synthesis of miR‐150‐5p and activating the ERK signalling pathway." (PMID 39466654, 2024). "Activation triggered by bone sialoprotein (BSP) on matrix metalloproteinase (MMP)-14 enhances the migratory and invasive potential of lung carcinoma cells through the PI3K/AKT/AP-1 axis." (PMID 39512767, 2024). "In a previous study, we determined that BSP induces the expression of metalloproteinase‐14 (MMP‐14) in lung cancer cells in vitro and in vivo, thereby increasing the likelihood of osteolytic bone metastasis." (PMID 39466654, 2024). "It has been reported that MMP‐14 plays a regulatory role in the development of osteolytic bone metastasis in cases of lung cancer." (PMID 39466654, 2024). "In the current study, we determined that BSP enhances anoikis resistance in human lung cancer cells by up‐regulating MMP‐14 production." (PMID 39466654, 2024). "The other MMPs including MMP1, MMP9 and MMP14 were differentially changed in three lung cancer cells depending on specific cell types." (PMID 34253166, 2021). "Our group also delved into the signaling pathways involved in the function of MMP14 in modulating immune response in lung cancer." (PMID 34868395, 2021). "Experiments such as western blot, qRT-PCR, colony-forming assay and Transwell assay confirmed that downregulation of MMP14 could inhibit the cloning, proliferation and invasion of lung cancer cells, thus confirming the results of bioinformatics." (PMID 40407957, 2025). "The in vitro results confirmed downregulation of MMP14 could inhibit the cloning, proliferation and invasion of lung cancer cells, thus confirming the results of bioinformatics." (PMID 40407957, 2025). "In addition, MMP14 can interact with bone sialoprotein to promote osteolytic bone metastasis in lung cancer." (PMID 40407957, 2025). "Moreover, MMP-14, also known as membrane-type 1 MMP (MT1-MMP), has been linked to tumor angiogenesis and metastasis in lung cancer by facilitating the degradation of basement membrane components and promoting the release of pro-angiogenic factors." (PMID 39493455, 2024).
lung carcinoma (continued). "FAM83A-AS1 was suggested to affect lung cancer cell invasion and migration through miR-150-5p/MMP14 signaling or miR-495-3p and may promote lung cancer progression through increasing FAM83A expression or glycolysis via regulating HIF-1α degradation." (PMID 35635086, 2022). "MMP14 was also demonstrated to serve as a tumor promotor in lung cancer." (PMID 34580602, 2021). "Survival assays showed there was no distinct association between MMP14 dysregulation and survival time of lung cancer patients." (PMID 34868395, 2021). "Strikingly, these cultures also express elevated Mmp10 mRNA, but no increase in Mmp2, Mmp7, Mmp9, Mmp11, Mmp12 or Mmp14, other Mmp species commonly linked to lung cancer." (PMID 22545096, 2012). "Similarly, MMP14 plays an important role in lung cancer bone metastasis." (PMID 38898429, 2024). "Thus, it appears that BSP promotes MMP‐14‐dependent anoikis resistance in lung cancer." (PMID 39466654, 2024). "MMP14–cetuximab APEC was evaluated in NOD/SCID mice xenografted with breast (MDA-MB-231), liver (SNU-475), or lung cancer cells (MGH-1088)." (PMID 37568582, 2023). "For instance, the high expression of MMP14 and CCL20 facilitates the cancer cell proliferation and metastasis of lung carcinoma." (PMID 35372503, 2022). "MMP-28 overexpression in vitro lead to increased MMP-2 and MMP-14 mRNA levels, constitutive MMP-2 activation, and revealed e-cadherin as a high-affinity substrate for proteasomal degradation in lung carcinoma cells." (PMID 34255809, 2021). "In the lung cancer mouse model, MMP14–cetuximab APEC-treatment did not prolong median survival, while overall survival was significantly improved in the intervention group despite the presence of right censoring." (PMID 37568582, 2023). "Once MMP-2 is active, it is released, while MMP-14 and TIMP-2 remain attached to the membrane; this event may explain the low levels of MMP-14 and TIMP-2 found in blood from lung cancer patients." (PMID 36213817, 2022). "Similarly, an overexpression of miR-133a in the lung cancer cell lines, A549 and NCI-H1299, results in the suppression of cell proliferation, migration, and invasion by targeting matrix metallopeptidase 14 (MMP14)." (PMID 36428980, 2022). "In the study, we found that MMP14 expression was distinctly upregulated in lung cancer specimens compared with nontumor lung specimens." (PMID 34868395, 2021). "To further assess the clinical significance of MMP14 in lung cancer, we measured the expression levels of MMP14 in 76 LUAD and paired adjacent non-tumor tissues using IHC." (PMID 33363004, 2020). "However, there is little evidence to support assertions that the MMP‐14‐miRNA axis plays a regulatory role in anoikis resistance in lung cancer." (PMID 39466654, 2024). "In addition to MMP-14, other ECM regulators, such as Procollagen C-Endopeptidase Enhancer 2 (PCOLCE2), a predictive marker for epithelial-to-mesenchymal transition and metastasis in lung cancer, were also observed with elevated synthesis levels in the dECM-tumors." (PMID 40166338, 2025). "Expression of MT1-MMP (MMP14) was not significantly altered in MSCs and PC9 lung cancer cells cultured alone or under co-culture conditions." (PMID 33119681, 2020).